INS (insulin)
Diseases named in the same sentence as INS in open-access papers (continued):
Sharing a sentence is not in itself a finding about the gene and the disease.
Hypoglycemia (continued). "In their preference study in insulin-treated patients the occurrence of hypoglycemia was most important for the patients." (PMID 33587221, 2021). "On the basis of information on the sialidase activity imaging in the pancreas, it was found that sialidase inhibitor can be used as an anti-diabetic drug that can avoid hypoglycemia, a serious side effect of insulin secretagogues." (PMID 33804798, 2021). "Based on the ability of V1bRs to promote glucagon release, we explored the possibility that V1bR signaling contributes to the counterregulatory increase in plasma glucagon levels triggered by insulin-induced hypoglycemia." (PMID 34752420, 2021). "Insulin suspension preceding the hypoglycemia is just one of a series of factors that should be evaluated when determining how to treat mild to moderate hypoglycemia events." (PMID 33535013, 2021). "pNETs were functional in 44% of patients, mostly due to insulin secretion resulting in hypoglycemia." (PMID 34025587, 2021). "Compared with medium-acting insulin, long-acting insulin analogs have greater advantages in terms of longer acting time, better fasting and pre-meal glycemic control, and a lower frequency of hypoglycemia." (PMID 34917025, 2021). "Hybrid closed loop insulin delivery promises hypoglycemia avoidance because insulin delivery is suspended when glucose levels fall, or are predicted to fall, below a specified threshold." (PMID 33628834, 2021). "Two of them had used insulin to induce hypoglycemia to have their family affection centered on them again." (PMID 34040920, 2021). "Compared to the conventional needles, SPN was associated with substantially reduced total daily insulin dose, HbA1c%, FBG, PPG, and a monthly number of confirmed hypoglycemia when using SPN." (PMID 33927957, 2021). "More importantly, perhaps, disabling CCKBVMH neurons with Cre-dependent tetanus toxin suppresses hepatic glucose production and the CRR to insulin-induced hypoglycemia." (PMID 34265067, 2021). "Reduced hypoglycemia (d = 0.47‐0.79), reduced basal insulin requirements (d = 0.48), and a smaller glucose coefficient of variation (d = 0.47) occurred with medium-large effect sizes from baseline to 9 months." (PMID 33628834, 2021). "A number of studies have reported higher rates of hypoglycaemia and intravenous dextrose use in babies born to insulin-treated women compared to women treated by metformin or diet." (PMID 34243753, 2021). "Better knowledge of the probable cardiotoxic effects of insulin-induced hypoglycemia is a crucial approach in lessening cardiotoxicity." (PMID 33898141, 2021). "The decline in plasma potassium during insulin-induced hypoglycemia is almost equally mediated by insulin-induced and catecholamine-induced cellular potassium uptake." (PMID 34085953, 2021). "Hyperlipidemias can also be treated by insulin therapy, but patients with IR are more difficult to treat, and need special care to prevent hypoglycemia." (PMID 34947937, 2021). "This evidence is concordant with those obtained from transgenic models such as mice lacking vesicular glutamate transporter 2 (VGLUT2) specifically in SF1 neurons since this genetic disruption attenuated recovery from insulin-induced hypoglycemia." (PMID 34201257, 2021). "The hyperinsulinemic-hypoglycemic clamp data further suggest that the usual direct effects of insulin on ghrelin cells to reduce ghrelin secretion in WT mice limits ghrelin’s full potential to protect against insulin-induced hypoglycemia." (PMID 34473648, 2021). "In one study, LGA (51 vs. 26%) and neonatal hypoglycemia (24 vs. 3%) were even more frequent in offspring of insulin-treated vs. diet-treated mothers." (PMID 35069449, 2021). "In both T1D and T2D, the ability of glucagon to counteract insulin-induced hypoglycemia has been shown to be impaired." (PMID 34752420, 2021).
Hypoglycemia (continued). "The main priorities to monitor for PWD were burden of self-management, symptom distress related to multiple side effects including gastro-intestinal symptoms, injection issues and hypoglycemia with the latter two issues being specific for insulin-treated PWD." (PMID 34507618, 2021). "Because of their pharmacological profile, insulin analogues can better mimic endogenous insulin production compared with human insulin, thus contributing to a decreased frequency of hypoglycemia and improved treatment satisfaction." (PMID 33905628, 2021). "Severe hypoglycemia still represents a serious problem in children, even though new insulin analogs, better insulin administration regimes, and close glucose monitoring have reduced its frequency." (PMID 34638984, 2021). "Although mild episodes of hypoglycemia occur 0.8 to 2 times per week in people with type 1 diabetes and people with insulin-treated type 2 diabetes, severe hypoglycemia rates range from 1.4 to 1.7 episodes per year." (PMID 34342593, 2021). "Patients treated with insulin or drug inducing hypoglycemia, consider hypoglycemia as a harmful element, which leads to their resistance and lack of acceptance of the pathology and relative therapies." (PMID 34572493, 2021). "Intriguingly, in our study during the prolonged fasting, the basal insulin rate for CSII was only lowered by ~4% that was sufficient to prevent hypoglycemia." (PMID 34295305, 2021). "Time in target glucose range was increased (78% vs 62%) and hypoglycaemia (<3.3 mmol/l) was reduced (0.6% vs 1.9%) with dual-hormone closed-loop use compared with insulin pump therapy alone." (PMID 33550442, 2021). "The proportion of Fos-positive, PNMT-immunoreactive (epinephrine-producing) chromaffin cells in the adrenal medulla and plasma epinephrine levels were quantified 2 h after insulin administration to establish that hypoglycemia activated the sympathoadrenal CRR." (PMID 34444787, 2021). "This prospective study's findings reveal that patients with T1DM can experience improvement in the level of insulin needles usability, HbA1c values, and hypoglycemia after a 12-week usage of the SPN." (PMID 33927957, 2021). "Among 694 participants administered with once-daily IDegAsp in five RCTs and 703 participants administered with once-daily basal insulin, 353 (50.9%) and 324 (46.1%) participants had at least one overall confirmed hypoglycemia event, respectively." (PMID 34564455, 2021). "Rapid-acting analogs are generally preferred for prandial insulin in multiple daily injection (MDI) regimens as they offer a reduction in hypoglycemia alongside decreased post-prandial blood glucose (BG)." (PMID 37745178, 2021). "While dietary sugar promotes insulin signaling and decreases Akh signaling to prevent hyperglycemia, ingestion of protein concomitantly increases both insulin and Akh to prevent insulin-induced hypoglycemia after protein-rich meals." (PMID 32448994, 2020). "For this issue, the role of hypoglycemia is central: a study has shown that for 75.5% of healthcare professionals fear of hypoglycemia is a barrier to insulin therapy." (PMID 32565924, 2020). "In fact, recent studies have reported that enhanced melatonin signaling caused by mutations in melatonin receptors suppresses insulin secretion in pancreatic beta cells, suggesting that melatonin inhibits insulin secretion and prevents nocturnal hypoglycemia." (PMID 33070478, 2020). "This role for ghrelin during the CRR to insulin-induced hypoglycemia aligns with its other well-described glucoregulatory actions." (PMID 33042003, 2020). "This is a great benefit of this method for the prevention of hypoglycaemia due to long-term intensive insulin therapy." (PMID 32005949, 2020). "An artificial pancreas is able to autonomously stop insulin when hypoglycaemia is detected and to restart insulin delivery when glucose levels recover." (PMID 32916984, 2020).
Hypoglycemia (continued). "In the current study, the blood glucose levels of the GDM- group were maintained in the normal range by dietary control or insulin treatment, and hypoglycemia still occurred in newborns." (PMID 32280713, 2020). "Conditioned hypoglycemia is due to the secretion of insulin activated by the cholinergic fibers of the vagus nerve (Porte, Girardier, Seydoux, Kanazawa, & Posternak, 1973; Woods, 1972)." (PMID 32232927, 2020). "In focal CHI, a localised lesion within the pancreas hypersecretes insulin and, importantly, hypoglycaemia resolution is possible through limited surgical resection of the lesion." (PMID 32874187, 2020). "The serum insulin and fatty acid concentrations during standardized fasting tests in hypoglycemia patients were also collected." (PMID 33133020, 2020). "Duration of T1DM, method of insulin administration, time in hypoglycemia, and time in range were the outcome measures analyzed in their dynamics across one year of interdisciplinary intervention." (PMID 33023137, 2020). "TBIR disease has been reported in Asians, and the characteristic clinical findings in Asian patients, namely, high incidence of hypoglycemia, low incidence of acanthosis nigricans, and low number of required insulin units, have also been reported." (PMID 32337291, 2020). "Studies using CGM have revealed that the percentage of hypoglycemic events is even higher than that previously appreciated, ranging from 57 to 79% in patients with T2DM on insulin therapy, with high percentage of nocturnal hypoglycemia." (PMID 32151247, 2020). "Hypoglycemia is a common medical emergency in the context of insulin treatment in diabetic patients and oral hypoglycemic agents such as sulfonylureas." (PMID 33457120, 2020). "Equivalent hypoglycemia, induced by lipopolysaccharide (LPS) or insulin, was sufficient to trigger cognitive impairment selectively in animals with existing neurodegeneration and glucose also mitigated those impairments." (PMID 32513828, 2020). "Nonetheless, half of the patients who wanted to go to the emergency room with hypoglycemia were those treated with insulin." (PMID 32774458, 2020). "Our results showed that both acute and chronic injection of high and low doses of RFRP-3 significantly weakened insulin-induced hypoglycemia between 15 and 30 min after insulin challenge." (PMID 32328034, 2020). "Another important issue is safety, where hypoglycemia, especially severe hypoglycemia, is the major concern among patients treated with insulin, because it can be lethal." (PMID 33086494, 2020). "Evaluating the changes in pancreatic islet function during treatment and timely adjustment of the drug dosage in patients who are sensitive to insulin therapy can reduce the occurrence of hypoglycemia." (PMID 33015194, 2020). "The other patients who developed hypoglycemia (21.1%) were on treatment or had previously received insulin treatment." (PMID 32813762, 2020). "We observed a greater number of patients with DKA and ESRD developing volume overload and hypoglycemia during insulin treatment compared with patients with preserved renal function." (PMID 32111715, 2020). "Data from the literature on diabetes mellitus treated with insulin show an increase in the occurrence of symptomatic hypoglycaemia from levels of 3.9 mmol/l and below." (PMID 32457534, 2020). "While AI is rapidly developing within the field of medical informatics, many of the systems presented in this article utilize traditional machine learning algorithms to adjust insulin therapy or predict hypoglycemia." (PMID 32517068, 2020). "Patients were switched from their current basal insulin to Gla-300 due either to inadequate glycaemic control or occurrence of hypoglycaemia." (PMID 32337298, 2020). "Among them, the total treatment time ≥ 7 days was a risk factor for hypoglycemia, and FBG ≥ 7 mmol/L and fasting insulin ≥ 9.30 mu/L were protective factors for hypoglycemia." (PMID 33015194, 2020).
Hypoglycemia (continued). "Although TXNIP functions as an adaptor for the basal GLUT4 endocytosis in order to prevent hypoglycemia under fasting conditions, insulin releases TXNIP from GLUT4 and prevents GLUT4 from being endocytosed in the postprandial state." (PMID 32476292, 2020). "MPM mice developed hypoglycemia and elevated serum insulin levels as they developed PanNETs, indicating that these PanNETs were insulinomas, similar to MPR PanNETs." (PMID 31160716, 2020). "Their results demonstrate that patients with insulin-treated T2DM with low postprandial C-peptide levels have markedly increased incidence of hypoglycemia in comparison to those with retained C-peptide levels." (PMID 33023555, 2020). "Patients with insulinoma manifest the symptoms and signs of hypoglycemia due to hypersecretion of insulin/proinsulin by the tumor cells." (PMID 32124259, 2020). "The rate of achieving adequate hypoglycemia with a single dose of insulin was significantly higher in the optimized group (65/70) than that in the conventional group (42/70) (92.9 vs. 60.0%, P < 0.001)." (PMID 32328036, 2020). "Insulin users are usually advised to consume carbohydrates to prevent hypoglycemia during and after PA." (PMID 32331210, 2020). "They proposed the hypoglycemia alarm system for preventing hypoglycemia before it happens with glucose concentration, insulin, and physical activity information." (PMID 33198170, 2020). "By assessing the area under the curve induced by dexamethasone, insulin, propranolol, clonidine and GHRH, the authors concluded that the potency of dexamethasone was similar to clonidine and greater than insulin-induced hypoglycemia." (PMID 33362716, 2020). "We showed that ghrelin-KO mice exhibit more pronounced and prolonged hypoglycemia than WT littermates when administered the same insulin dose in the form of a single bolus." (PMID 33042003, 2020). "This slow appearance in the periphery mediates an early transient hepato-centric insulin action and blunts hypoglycaemia in dogs in response to overdosing." (PMID 32719315, 2020). "Loss of Prkar1a in the Sur1-/- mouse model of KATP hyperinsulinism significantly attenuated fasting induced hypoglycemia, decreased the insulin/glucose ratio, and also increased the hepatic expression of Kiss1 by more than 10-fold." (PMID 32735622, 2020). "We extensively reviewed the evidence of the CB being implicated in the regulation of blood pressure and glucose metabolism, acting on the counterregulatory responses to hypoglycemia and mediating insulin/glucagon secretion." (PMID 32698380, 2020). "His extremely high-dose insulin requirement “resolved” at day 9, and the insulin infusion rate was rapidly reduced, avoiding hypoglycemia." (PMID 33066762, 2020). "Infants with PSS had lower basal levels of GH, and GH release to insulin-stimulated hypoglycemia was inadequate in 5 of 7 with PSS." (PMID 33117295, 2020). "Fasting rodents that received AIRAs showed hypoglycemia within 2 hours, and this persisted for up to 24 hours, suggesting an acute effect similar to that of insulin administration." (PMID 32813762, 2020). "Dextrose treats the hypoglycemia, provides energy substrate required for metabolism, and stimulates insulin secretion while suppressing glucagon secretion." (PMID 32560535, 2020). "It is interesting to note that no GEMCGM participants experienced level 2 hypoglycemia, whereas 2 RC participants, either having gone on insulin or glipizide, experienced 3 level 2 hypoglycemia events per patient during follow-up." (PMID 33094208, 2020). "Congenital hyperinsulinism (CHI) is a rare disease characterized by persistent hypoglycemia as a result of inappropriate insulin secretion, which can lead to irreversible neurological defects in infants." (PMID 33193079, 2020).
Hypoglycemia (continued). "Insulin pump therapy (IPT) is one of the options used to control this disease and reduces one of the most frequent complication associated with treatment: hypoglycemia, which has also a great impact on life quality and clinical status of patients." (PMID 32832557, 2020). "For example, consider a scenario in which a patient overestimates the insulin bolus for a meal (for instance, because the patient overestimates meal carbs) and because of the excessive insulin dose experiences hypoglycemia 3 h after the meal." (PMID 32664432, 2020). "For these patients, medical staff should always be mindful of their susceptibility to hypoglycemia when prescribing insulin or OHA and educate them on the prevention of hypoglycemia." (PMID 32774458, 2020). "This is because hypoglycemia and weight gain were cited as barriers to the use of insulin treatment, negatively impacting QoL and adherence to treatment." (PMID 32187271, 2020). "Among the ITTs, adequate hypoglycemia was successfully induced with a single dose of insulin in 107 patients, including 42 in the conventional group and 65 in the optimized group." (PMID 32328036, 2020). "We previously reported that older male patients with newly diagnosed T2D have an increased nocturnal hypoglycemia during continuous subcutaneous insulin infusion therapy." (PMID 32090123, 2020). "Hydroxychloroquine has a proven hypoglycemic effect, therefore also in this case the insulin treatment must be very carefully managed in order to avoid episodes of hypoglycemia." (PMID 32690029, 2020). "Severe hypoglycemia is a life-threatening problem for diabetic patients with intensive insulin therapy." (PMID 32358493, 2020). "Some of the first evidences that insulin is capable of stimulating CB chemoreceptors came from studies dedicated to evaluate the CB glucose sensing properties and in where hypoglycemia was achieved through insulin administration." (PMID 33353562, 2020). "Insulin assays are routinely ordered for newborns and children suffering from persistent hypoglycemia and access to quick results, while still minimizing blood volume, is desirable under such conditions." (PMID 31906315, 2020). "In general, the body has protective mechanisms to prevent hypoglycemia during a period of energy shortage that includes lowering serum insulin levels and stimulating glucagon, cortisol, epinephrine, and growth hormone secretion." (PMID 32560535, 2020). "Several studies showed reduced weight gain in women with GDM treated with metformin vs. those treated with insulin, along with a reduction of severe hypoglycemia and pregnancy-induced hypertension (PIH)." (PMID 32625081, 2020). "Hyperinsulinemic hypoglycemia (HH) is a heterogeneous condition with dysregulated secretion of insulin from the β-cells during hypoglycemia." (PMID 33679602, 2020). "During a glucose tolerance test (GTT) at 2 weeks post-injection, mice exposed to 200 μg/kg TCDD showed severe hypoglycemia and a dramatic decrease in plasma insulin levels." (PMID 31996693, 2020). "This was achieved while using less insulin and with a reduction in clinically relevant hypoglycemia." (PMID 33202616, 2020). "This is a bit odd that, unlike previous studies in western countries, our patients seem to need much more insulin to achieve hypoglycemia in ITTs." (PMID 32328036, 2020). "Cerebral blood flow increased by 42% following insulin injection with a delay of 17 ± 10 min, while the onset of hypoglycemia symptoms was delayed by 24 ± 11 min." (PMID 33277531, 2020). "In IKH, which typically presents around 6 months of age, p-insulin is adequately suppressed during hypoglycemia." (PMID 33679602, 2020). "Defects in these genes are responsible for the failure of β-cells to respond to normal regulatory mechanisms, leading to inappropriate and excessive insulin release despite low blood glucose concentrations resulting in frequent episodes of hypoglycemia." (PMID 33193079, 2020).